MCF2 (MCF.2 cell line derived transforming sequence)
Description:
Guanine nucleotide exchange factor (GEF) that modulates the Rho family of GTPases. Promotes the conversion of some member of the Rho family GTPase from the GDP-bound to the GTP-bound form. Isoform 1 exhibits no activity toward RHOA, RAC1 or CDC42. Isoform 2 exhibits decreased GEF activity toward CDC42. Isoform 3 exhibits a weak but significant activity toward RAC1 and CDC42. Isoform 4 exhibits significant activity toward RHOA and CDC42. The truncated DBL oncogene is active toward RHOA, RAC1 and CDC42.
Synonyms: DBL; ARHGEF21
Tractability: Antibody: the Human Protein Atlas places it where antibodies can reach. PROTAC: ubiquitination databases record sites on it.
Gene: Protein-coding gene on chromosome X (139,581,770 to 139,708,216, reverse strand). Ensembl gene ENSG00000101977.
Subcellular location: Cytoplasm; Membrane (Isoform 1); Membrane (Isoform 3)
Subcellular location (Human Protein Atlas): Cytosol; Plasma membrane; Nucleoplasm
Pathways (Reactome):
Signal Transduction: Axonal growth inhibition (RHOA activation); CDC42 GTPase cycle; G alpha (12/13) signalling events; NRAGE signals death through JNK; RAC1 GTPase cycle; RAC2 GTPase cycle; RAC3 GTPase cycle; RHOA GTPase cycle; RHOB GTPase cycle; RHOC GTPase cycle; RHOG GTPase cycle
Gene Ontology:
Molecular function: protein binding; guanyl-nucleotide exchange factor activity
Biological process: dendrite development; negative regulation of axonogenesis; regulation of small GTPase mediated signal transduction; intracellular signal transduction
Cellular component: cytosol; plasma membrane; cytoplasm; cytoskeleton; membrane
Homologues: Orthologues: chimpanzee MCF2 (99% identical), macaque MCF2 (95% identical), pig MCF2 (88% identical), rabbit MCF2 (81% identical), dog MCF2 (80% identical), rat Mcf2 (77% identical), mouse Mcf2 (76% identical), guinea pig MCF2 (74% identical), tropical clawed frog mcf2 (53% identical), zebrafish mcf2a (51% identical), zebrafish mcf2b (44% identical). Paralogues in human: MCF2L (45% identical), MCF2L2 (37% identical), TRIO (22% identical), KALRN (21% identical), PLEKHG4B (20% identical), PLEKHG4 (19% identical), TIAM2 (17% identical), ARHGEF40 (16% identical), TIAM1 (16% identical), SPATA13 (15% identical), SESTD1 (13% identical), PLEKHG1 (13% identical), and 10 more.
Diseases named in the same sentence as MCF2 in open-access papers:
MCF2 is named in the same sentence as 5 diseases in open-access papers, as found by Europe PMC text mining. Sharing a sentence is not in itself a finding about the gene and the disease. The quoted sentences say what the papers report.
cognitive decline (1 paper, 2025). "When focusing on X-linked genes, sex significantly moderated MCF2, HDAC8, SLC10A3, and FTX on tau tangle burden or cognitive decline in the DLPFC." (PMID 40166028, 2025).
melanoma (1 paper, 2019). A malignant, usually aggressive tumor composed of atypical, neoplastic melanocytes. "Importantly, we have recently described experiments that functionally validated the role of four of these candidates (VAV1, MCF2, BRAF, RAF1) in driving vemurafenib resistance in human melanoma cell lines." (PMID 31208320, 2019).
Obesity (1 paper, 2022). Accumulation of substantial excess body fat. "Four of the differentially methylated regions were in genes previously found to be associated with obesity, metabolic regulation, and glycemic control (LRRC8D, SOSTCD1, MORN3, and MCF2)." (PMID 36474183, 2022).
MCF2 also shares sentences with these, for which no sentence is quoted: tumor (2 papers); atherosclerosis (1).